HPSE (heparanase)
Diseases named in the same sentence as HPSE in open-access papers (continued):
Sharing a sentence is not in itself a finding about the gene and the disease.
cancer (continued). "Mounting evidence indicates that HPSE protein is a key player in cancer progression." (PMID 36130926, 2022). "Actually, matrix enzymes such as metalloproteinases (MMPs) and heparanase are responsible for degradation of the extracellular matrix, which prompts epithelial-to-mesenchymal transition thus facilitating cancer cell motility, invasion and metastasis characteristic of the MDA-MB-468 cells." (PMID 35053613, 2022). "Indeed, an increased abundance of heparanase is seen in exosomes isolated from cancer patients compared to those from healthy individuals, suggesting enhanced exosomal release via the syndecan–syntenin–ALIX pathway." (PMID 35884411, 2022). "ARIEL in leukemia, HPSE in different cancer types, and P2RY2 in bladder cancer are other examples of eRNAs targeted by knockdown approaches that may serve as new therapeutic targets for cancer treatment." (PMID 36287118, 2022). "Heparanase is elevated in various pathological conditions, primarily cancer and inflammation." (PMID 35805119, 2022). "Mechanism-based HPSE inhibitors reduce cancer metastasis in vivo." (PMID 35881786, 2022). "That may be analogous to the HPSE1 role in various aspects of cancer metastasis (i.e., while in some cancer phases, heparanase assists ECM degradation; in others, it enhances neovascularization)." (PMID 36340029, 2022). "Appropriate concerns might be raised because heparanase contributes to the pathogenesis of cancer and certain inflammatory diseases." (PMID 36293542, 2022). "It is worth mentioning here the role of heparanase in augmenting angiogenesis, another hallmark of cancer, through both its enzymatic and non-enzymatic activities." (PMID 35327524, 2022). "Inhibitors targeting HPSE also have a high potential in managing various cancers." (PMID 36130926, 2022). "Heparanase inhibitors have been developed, some of which are in trials as cancer therapeutics." (PMID 33561383, 2021). "The human heparanase variant (T5) lacking enzymatic activity has protumorigenic properties, indicating the enzyme’s complex role in cancer pathogenesis." (PMID 33800172, 2021). "As such, heparanase inhibitors are being evaluated clinically as anti-cancer therapeutics." (PMID 33959505, 2021). "This provides useful information that heparanase is a potent protein for cancer progression." (PMID 34070058, 2021). "As attractive HPSE inhibition may seem for cancer attenuation, it is of importance to note the critical role of the enzyme on the infiltration of activated NK cells to primary tumors and metastasis sites." (PMID 33809973, 2021). "Targeting HPSE has already been shown to efficiently reduce cancer progression in patients." (PMID 34677445, 2021). "The relationships between HPSE expression and prognosis of different cancers in PrognoScan." (PMID 34461608, 2021). "Heparanase activity was found to be included in human cancer development and growth." (PMID 33411145, 2021). "Additionally, these newly reported activities of HPSE can help explain the documented roles of HPSE in cancer progression." (PMID 33621216, 2021). "This, and other mechanisms utilized by heparanase to promote tumorigenesis, have turned this enzyme into a promising drug target and heparanase inhibitors are currently being evaluated in clinical trials as anti-cancer drugs." (PMID 33959505, 2021). "HPSE can also regulate autophagic mechanism of cancer cells." (PMID 34677445, 2021). "Cancers can express heparanase to cleave the heparin sulfate proteoglycan chain." (PMID 34234872, 2021). "Mammalian cells express a single dominant functional heparanase (HPSE) that cleaves heparan sulfate (HS), contributes to disassembly of the extracellular matrix, releases HS-bound effector molecules, and thereby facilitates cancer metastasis and inflammation." (PMID 34685503, 2021). "Moreover, heparanase levels correlate with shorter postoperative survival of cancer patients, encouraging the development of heparanase inhibitors as anti-cancer drugs." (PMID 34199150, 2021).
cancer (continued). "The hit compounds presented from this in silico investigation could act as potent Heparanase inhibitors and further serve as lead scaffolds to develop compounds targeting Heparanase upregulation in cancer." (PMID 34156395, 2021). "Moreover, heparanase has been shown to affect cancer angiogenesis, invasion, and autophagy and partly through syndecan-1-dependent mechanisms to modulate inflammation-associated tumorigenesis." (PMID 33800172, 2021). "The upregulation of heparanase upon treatment with these therapeutics may mean that combining with heparanase inhibitors could have synergistic benefits for anti-cancer treatments." (PMID 34681753, 2021). "Heparanase, which degrades extracellular matrix components is upregulated in many cancers." (PMID 34439467, 2021). "In head and neck (H&N) cancer, heparanase expression is inversely correlated with patient status." (PMID 33959505, 2021). "HPSE expression has been shown to be elevated in virtually all human carcinomas examined." (PMID 34578329, 2021). "According to all these studies, high levels of heparanase could be used as predictive and prognostic molecular marker for cancer." (PMID 31963505, 2020). "HPSE affects glucose metabolism in several disease settings, which could suggest a similar role in cancer." (PMID 33256730, 2020). "The mutant inactive form of heparanase is involved in adhesion-dependent signaling which in turn may promote chemoresistance of cancer cells by increasing the side population." (PMID 32477959, 2020). "To sum up, this study has illustrated heparanase as a target of hinokitiol, and we believe that hinokitiol may be a potent anticancer candidate as it acts against cancer-promoting pathways namely, P-Akt and P-Erk, that drives the expression of heparanase." (PMID 32132875, 2020). "Enoxaparin sodium’s mode of action on the extracellular matrix will slow the cancer’s invasion process (related to the action of heparanase) and could explain the results obtained in the present study." (PMID 33312942, 2020). "HPSE has been extensively studied as a potential anti-cancer drug target." (PMID 32957513, 2020). "This, and many other mechanisms utilized by heparanase to promote tumorigenesis, have turned this enzyme into a promising drug target and heparanase inhibitors are currently being evaluated in clinical trials as anti-cancer and anti-viral drugs." (PMID 33585253, 2020). "Heparanase was found to be expressed in most malignant tumors." (PMID 32121387, 2020). "Due to the important role of heparanase in HS post-biosynthetic modification and catabolism, we focus on the possibility to target heparanase, at both extracellular and intracellular levels, a strategy that can be applied to many conditions, from inflammation to cancer and neurodegeneration." (PMID 31963505, 2020). "In addition, targeting HSPG biosynthetic and post-translational modifying enzymes such as endosulfatases and heparanase represents an effective therapeutic intervention for cancer treatment." (PMID 32916872, 2020). "Indeed, the HS mimetics PI-88, PG545, and M402 have been shown to exert anti-angiogenic and antimetastatic effects by inhibiting heparanase in several types of cancers." (PMID 32916872, 2020). "In addition to heparanase, sulfatases that remove the O-sulfate group from HS chains have been explored as targets for cancer therapy." (PMID 32916872, 2020). "The inhibition of heparanase eliminates the cleavage of HS chains and the release of bioactive molecules such as, FGFs, and VEGF, to disrupt the downstream events that are associated not only with the progression of cancer but also with cancer metastasis." (PMID 32010611, 2019). "Does the tumorigenic effect of heparanase change during cancer progression?" (PMID 31110966, 2019). "How do the pro/anti-tumorigenic effects of heparanase differ across different cancer types?" (PMID 31110966, 2019).
cancer (continued). "Although the apoptosis evading mechanisms of different cancer cells may vary regarding the factors that come into play, heparanase's play in conferring a common apoptosis resistant fate may extend to other cancer cells." (PMID 31044520, 2019). "As has been highlighted in recent reviews, it is now known that heparanase is involved in a range of pathologies in addition to cancer, including inflammation, diabetes, bone necrosis, liver fibrosis, amyloidosis and Alzheimer's disease, and in the infection and spread of numerous viruses." (PMID 31850210, 2019). "This study suggested that heparanase may directly interfere with apoptotic pathways, and so could protect cancer cells from apoptosis during therapy." (PMID 31850210, 2019). "Furthermore, the increase in heparanase expression in multiple cancer types results in the cleavage of HS chains and release of mediators involved in these events." (PMID 32010611, 2019). "If heparanase has the potential to alter gene transcription either by directly binding DNA or indirectly by regulating methylation patterns, cancer cells with high levels of endogenous heparanase should express a different pattern of genes than cells with low or normal heparanase levels." (PMID 31850210, 2019). "A compelling number of studies have tied heparanase with inflammatory diseases and cancer." (PMID 31044520, 2019). "Hence, even in the presence of the drug, nuclear heparanase would continue to protect cancer cells from apoptosis by its ability to down-regulate the transcription of pro-apoptotic genes, a function that does not involve enzymatic activity." (PMID 31850210, 2019). "Considerations such as those that heparanase is the product of a single gene and is upregulated in several human malignant tumors, in activated pro-inflammatory cells, and in a number of other pathological conditions, make heparanase an interesting target for drug development." (PMID 31362364, 2019). "Answering these questions may help guide the appropriate use of heparanase inhibitors, and the use of heparanase-assisted therapies for the treatment of cancer." (PMID 31110966, 2019). "While this manuscript was in preparation an extensive review on heparanase in cancer highlighting the numerous synthetic and chemically modified natural compounds that have been produced as potential drugs targeting heparanase was published, accordingly we will take a different approach here." (PMID 31850210, 2019). "Notably, cancer patients exhibiting high levels of heparanase had a significantly shorter postoperative survival time than patients whose tumors exhibit low levels of heparanase." (PMID 30627323, 2018). "It has been demonstrated that heparanase may play an important role in promoting many cancer cells’ metastasis." (PMID 30135409, 2018). "Studies performed in mouse models of colon and pancreatic carcinomas exemplified how heparanase may represent a mechanistic link coupling inflammation and cancer." (PMID 30413079, 2018). "Importantly, number and size of autophagosomes and levels of LC3 were noticeably decreased by PG545, suggesting that heparanase functions to promote autophagy in AP in cancer cells." (PMID 28386074, 2017). "In addition, an analysis of BPTF and HPSE expression in human cancers from the TCGA data sets revealed a highly significant correlation between high BPTF expression and high HPSE expression in several cancer types including breast (see arrow)." (PMID 28969075, 2017). "Heparanase, therefore, emerges as a potential new target in AP, and heparanase inhibitors, now in phase I/II clinical trials in cancer patients, may prove beneficial also in AP." (PMID 28386074, 2017). "To investigate whether heparanase expression has a similar effect on TGF‐β1 activity, we examined TGF‐β1‐stimulated signaling pathways in human cancer cells that stably overexpress heparanase." (PMID 28286736, 2017).
cancer (continued). "Overall, we identified biologically active heparanase inhibitor which could serve as a lead structure in developing compounds that target heparanase in cancer." (PMID 28359266, 2017). "Further development of this novel class of heparanase inhibitors and optimization to maximize their affinity, pharmacokinetics and oral availability will provide a unique opportunity for development of innovative anti-cancer therapeutics." (PMID 28359266, 2017). "The significance of BPTF, and by extension NURF, regulation of HPSE in cancer could have broader implications." (PMID 28969075, 2017). "Furthermore, several studies have found that HPSE expression is elevated in treatment-resistant cancer cells." (PMID 28388549, 2017). "Given the diverse effects of heparin-like compounds, these studies indicate the significance of designing chemically novel, highly selective and biologically active heparanase inhibitors to potently target various types of cancers and possibly inflammatory diseases." (PMID 28359266, 2017). "Together with our current findings, these studies support the notion that heparanase may contribute to the promotion of drug resistance in many types of cancer." (PMID 26624982, 2016). "Because heparanase promotes metastasis RONEPARSTAT could also be potentially used to target heparanase-driven metastasis in different cancers." (PMID 26624982, 2016). "Roneparstat and necuparanib, heparanase inhibitors obtained from heparin and currently being tested in man as a potential drugs against cancer, contain in their structure glycol-split uronic acid moieties probably responsible for their strong inhibitory activity." (PMID 27886097, 2016). "Together, these findings raise the exciting possibility that the efficacy of anti-cancer drugs may be enhanced when combined with the use of heparanase inhibitors." (PMID 27408707, 2016). "However, there is insufficient data regarding heparanase expression in the metastatic lesions that are the prime target for anti-cancer therapeutics." (PMID 27732945, 2016). "However, while the presence of heparanase at high levels has been documented in many types of cancers, its abundance in the resulting metastases has not been sufficiently resolved." (PMID 27732945, 2016). "Upregulation of heparanase has been reported in an increasing number of human cancer tissues." (PMID 26569485, 2015). "The results uncover a potential route for heparanase function in cancer and inflammation." (PMID 24465803, 2014). "In addition to its function in cancer progression, heparanase enzyme also plays a major role in inflammation per se and carcinogenesis related to inflammatory process." (PMID 25295847, 2014). "Overexpression of heparanase in pancreatic adenocarcinomas (PDAC) was identified several years ago when investigators discovered that this may facilitate cancer cell invasion and enhancement of metastatic dissemination." (PMID 25105093, 2014). "Despite their shared substrate and significance in cancer progression, it is important to note that the pH optima of heparanase (pH 5) and the Sulfs (pH 7–8) preclude them from being at their most active in the same microenvironment compartment, or at the same time." (PMID 25105093, 2014). "Recently, it was discovered that HPSE inhibitors could effectively suppress the invasion and metastasis of some malignant tumors." (PMID 23308126, 2013). "Due to its multiple roles, heparanase is seen as a target in cancer treatment." (PMID 23984412, 2013). "These genes have a strong correlation with angiogenesis (Hif1a, FLT1) and lead to alterations of the extracellular matrix and remodeling of subepithelial and subendothelial basal membranes (heparanase, HPSE) and therefore seem to be directly involved in the aggressiveness of cancers." (PMID 23704979, 2013). "Several factors regulate heparanase gene expression in cancer cells." (PMID 23984412, 2013).
cancer (continued). "Because recent studies indicate the feasibility of shRNA-mediated TGS in mammalian cells, in order to further investigate the effects of heparanase TSS-targeted siRNA on cancer cells, the shRNA constructs were established and transfected into PC-3, EJ and SGC-7901 cells." (PMID 22363633, 2012). "In addition to its function in cancer progression, heparanase enzyme also plays a major role in the activity of inflammatory cells." (PMID 22719856, 2012). "Astrocytes may also contribute to the invasiveness of cancer cells in the brain by producing heparanase, an enzyme that degrades heparin sulfate proteoglycans in the extracellular matrix." (PMID 24213237, 2012). "To identify the paracrine factors responsible for T47D carcinoma cell growth stimulation we treated the co-cultures with neutralizing antibodies to eleven factors implicated in stroma-carcinoma interactions (FGF-2, HB-EGF, Heparanase-1, HGF, IGF-1, IGF-2, MT1-MMP, PDGF, SDF-1, TGF-β1, and Wnt-1)." (PMID 23056402, 2012). "Heparanase over-expression inversely correlates with survival of patients with gastric, pancreatic, cervical, colorectal, bladder and prostate cancer." (PMID 22133010, 2011). "Resolving the heparanase crystal structure will accelerate rational design of effective inhibitory molecules and neutralizing antibodies, paving the way for advanced clinical trials in patients with cancer and other diseases involving heparanase." (PMID 23908791, 2011). "In addition, the in vitro invasion and metastasis of cancer cells were attenuated after knock-down of heparanase." (PMID 20137078, 2010). "Previous reports have shown that heparanase (HPA), an endo-h-D-glucuronidase, has the ability to cleave the heparan sulfate chain of HSPGs, and is one of the key enzymes involved in the invasion and metastasis of malignant tumors." (PMID 20137078, 2010). "Moreover, transfection of heparanase-specific siRNA attenuated the in vitro angiogenesis of cancer cells in a dose-dependent manner." (PMID 20137078, 2010). "Interestingly, cancer cells produce enzymes that are known to degrade the endothelial glycocalyx, such as heparanase and hyaluronidase." (PMID 20574516, 2010). "Heparanase is an enzyme known to promote the progression of many cancers." (PMID 19305494, 2009). "However, in inflammed or cancer tissue and in several cancer cell lines the expression of heparanase has been shown to be elevated and the high expression of heparanase has been linked to highly invasive cancers." (PMID 19171023, 2009). "Moreover, increased heparanase mRNA expression correlates with reduced postoperative survival of cancer patients." (PMID 18647407, 2008). "Heparanase has been strongly correlated with metastatic potential in human cancer probably by disrupting the structure of basement membranes and by releasing HS saccharide growth factor complexes from the pericellular matrix enabling their unrestricted access to cell-surface receptors." (PMID 17437011, 2007). "Heparanase expression is also evident in inflammation, angiogenesis and cancer metastasis." (PMID 11953884, 2002). "In addition, heparanase is involved in regulating SDC1 loading in exosomes, evident by the high content of SDC1 in exosomes secreted by heparanase-high expressing cells vs. heparanase-low expressing cells, with subsequent impacts on endothelial cells and cancer progression." (PMID 36980680, 2023). "Therefore, targeting HPSE is considered as a promising therapeutic strategy for cancer treatment." (PMID 36157032, 2022). "Notably, heparanase activity has been correlated to various human cancers’ metastatic potential." (PMID 33800172, 2021). "Moreover, most likely higher post-treatment heparanase concentrations in ER/PR negative cancers was associated with chemo-resistant cancer cells and most likely with treatment failure." (PMID 34070058, 2021). "Thus, in immune cancer therapy, heparanase could be a vital therapy target by either exploiting or inhibiting its activity." (PMID 33800172, 2021).